SIM1 (SIM bHLH transcription factor 1)
Diseases named in the same sentence as SIM1 in open-access papers (continued):
Sharing a sentence is not in itself a finding about the gene and the disease.
Obesity (continued). "Genes downstream of SIM1 have similarly been associated with both obesity and neurological phenotypes, suggesting that modulating this pathway may contribute to obesity, ASD, and their comorbidity." (PMID 39019033, 2024). "SIM1 loss of function has been associated with obesity and neurobehavioral deficits; in one study that identified 13 obese individuals with rare, de novo SIM1 mutations, 11 also presented with neurobehavioral abnormalities including impaired concentration and emotional lability." (PMID 39019033, 2024). "An association of SIM1 variants with early-onset obesity in children was demonstrated, but the association of SIM1 with hypertension was currently unknown." (PMID 36869404, 2023). "Targeted deletion of miR-7 in Single-minded homolog 1 (Sim1) neurons, a critical component of the hypothalamic melanocortin pathway, causes hyperphagia, obesity and increased linear growth, mirroring Sim1 and Melanocortin-4 receptor (MC4R) haplo-insufficiency in mice and humans." (PMID 36175420, 2022). "SIM1 mutations cause of monogenic obesity, and 13 SIM1 gene variants are found in obese patients." (PMID 33826123, 2022). "Sim1 haplodeficiency or postnatal deficiency of Sim1 causes early onset obesity with hyperphagia." (PMID 35020776, 2022). "The most prominent obesity phenotype occurred upon the Sim1 neuron-specific loss of miR-7." (PMID 36175420, 2022). "In rodents, loss of SIM1 neurons causes obesity with hyperphagia and decreased energy expenditure." (PMID 33557413, 2021). "Inhibition of Gs in SIM1‐expressing neurons is sufficient to cause obesity." (PMID 30643718, 2019). "SIM1 also plays an important role in the regulation of energy homeostasis by interacting with the melanocortin signalling pathway and loss-of-function variants in this gene are one of the few known causes of monogenic obesity in both humans and mice." (PMID 30991789, 2019). "Recently, it has been reported that chromosomal abnormalities such as translocation between chromosome 1p22.1 and 6q16.2, deletion of the 6q16.2 region and heterozygous point mutations in the SIM1 region are responsible for early-onset severe obesity in humans." (PMID 30991789, 2019). "The aim of our study was to search for SIM1 mutations in children with early-onset severe obesity; and, to describe detailed metabolic phenotypes of the mutation carriers and compare their phenotypes with the phenotypes for obese individuals not carrying SIM1 variant." (PMID 28472148, 2017). "Recently, it was shown that point mutations in SIM1 cause monogenic obesity as well." (PMID 28472148, 2017). "Moreover, as a part of the SIM1 mutation carriers has additional symptoms, also 26 patients with severe early onset obesity and learning disabilities or dysmorphic features of Prader-Willi-like syndrome were included." (PMID 28472148, 2017). "For example, both CNVs and SNVs of SIM1 are associated with obesity in humans." (PMID 28859103, 2017). "In SIM1 deletion heterozygous mice there is impaired development of the paraventricular nucleus of the hypothalamus, with reduced melanocortin-4 receptor and oxytocin expression, in association with hyperphagic obesity." (PMID 28859103, 2017). "In this study, we screened the functional regions of SIM1 in severely obese children of Slovak and Moravian descent to determine if genetic variants within SIM1 may influence the development of obesity in these populations." (PMID 28472148, 2017). "However, to date, the contribution of SIM1 mutations to the obesity phenotype has only been studied in a few populations." (PMID 28472148, 2017). "In humans, haploinsufficiency of SIM1 causes early-onset obesity." (PMID 24260538, 2013). "Sim1 deficiency is associated with hyperphagic obesity and normal energy expenditure." (PMID 22558467, 2012). "Several missense variants of SIM1 may underpin a monogenic form of obesity." (PMID 40428410, 2025).
Obesity (continued). "Therefore, it is possible that the loss of CRTCs in MeA might cause hyperphagia and obesity in Sim1-CRTCDKO mice." (PMID 35020776, 2022). "Moreover, few point mutations in SIM1 have been recognized as a cause of monogenic obesity." (PMID 36452324, 2022). "Moreover, SIM1 gene mutations also cause obesity and hyperphagia in both rodents and humans." (PMID 33557413, 2021). "Mutations associated with monogenic obesity follow autosomal recessive (LEP, LEPR, POMC, and PCSK1) or autosomal dominant (MC4R, SH2B1, SIM1, GNAS) modes of inheritance." (PMID 41751424, 2026). "The results underscore the importance of including the SIM1 gene in genetic testing panels for children with severe obesity and hyperphagia, enabling precise diagnosis and potential future personalized management." (PMID 41516406, 2026). "This indicates that partial loss of SIM1 function in heterozygotes is sufficient to drive hyperphagia-induced obesity as a result of distal DNA interactions made by the SIM1 PAS-A loop." (PMID 41495897, 2026). "In order to investigate the biological consequence of PAS-A loop DNA binding mutant R171H and its possible contribution to hyperphagia induced obesity we generated a knock-in mouse model for SIM1.R171H." (PMID 41495897, 2026). "SIM1 acts downstream of MC4R, and both can cause monogenic obesity via autosomal dominant inheritance." (PMID 40428410, 2025). "Seven publications reported outcomes of MBS in patients with obesity caused by rare variants in LEPR, MC4R, NCOA1, PCSK1, POMC, SH2B1, or SIM1." (PMID 40560452, 2025). "It was found that the expressions of ENPP1, MC3R, and SIM1 were significantly different between controls and obesity." (PMID 39351493, 2024). "The evaluation of deletions and duplications, in regions associated with obesity, is possible by assessing genes LEPR, POMC, SIM1, LEP, MC4R, MC2R, and MC3R, and in the 16p11.2 region by MLPA." (PMID 39458556, 2024). "By contrast, deleting Bdnf from Sim1-lineage neurons including the PVH resulted in a more severe obesity phenotype." (PMID 37956053, 2023). "At the physiological phenotype level, CRISPRa has also been used to increase the transcription of obesity risk genes SIM1 and MC4R, and to successfully rescue haploinsufficient obesity in mouse models—with the effects persisting up to 9 months post-treatment." (PMID 36792602, 2023). "In a study of 25 obese Guadeloupean patients, 5 heterozygous variants in 4 monogenic obesity genes (MC4R, NTRK2, SH2B1, and SIM1) were detected with a prevalence of 10%." (PMID 37329217, 2023). "Using a homozygous Rai1 conditional knockout (Rai1-cKO) mice, we found that Rai1 deletion in either subcortical excitatory neurons (vGlut2+) or single-minded homolog 1 (Sim1+) neurons induced obesity in mice." (PMID 37956053, 2023). "CREB mediates the effects of canonical MC4R signalling through the Gαs–cAMP–PKA cascade, and mice with genetic deletion of Creb1 in Sim1 neurons develop obesity, impaired thermogenesis, and reduced AVP expression." (PMID 36175420, 2022). "The addition of lard (dietary fat) to the AIN93 standard diet induced obesity in Sim1-CRTCDKO mice, indicating that CRTCs in Sim1 cells play an important role in the regulation of dietary fat-induced satiety or dietary fat-induced suppression of food intake." (PMID 35020776, 2022). "When challenged with chronic HFD feeding, obesity was significantly exacerbated in Sim1-cre;mir-7fl/fl mice of both sexes." (PMID 36175420, 2022). "Mice and humans with MC4R and SIM1 haplo-insufficiency develop hyperphagia, obesity and increased linear growth." (PMID 36175420, 2022). "The obesity phenotype of VMH AAV GPR88* mice was comparable to that of mice in which GPR88* is exogenously expressed in Sim1‐expressing neurons within the PVN region." (PMID 34783461, 2022). "Studies in mice further confirmed that knocking out Sim1 gene induced obesity and hyperphagia, probably through melanocortin receptor." (PMID 33826123, 2022).
Obesity (continued). "This maintenance of normal glucose tolerance, in spite of obesity and insulin resistance, was correlated with marked hyperinsulinemia in Sim1-cre;mir-7fl/fl mice." (PMID 36175420, 2022). "Since the SIM1 plays a role in the long-term regulation of food intake and energy expenditure, its reduced activity is manifested phenotypically as profound obesity and increased linear growth." (PMID 33799876, 2021). "A double transgenic mouse was generated in a Sim1 heterozygous background, which normally develops obesity." (PMID 35097003, 2021). "It was shown that SIM1 haploinsufficiency in mice induces hyperphagia (abnormally increased appetite for consumption of food) leading to obesity and developmental abnormalities of the brain." (PMID 33799876, 2021). "It has been shown that transgenic mice with overexpressed SIM1 are resistant to diet-induced obesity, which supports a post developmental, physiologic role for SIM1 in feeding regulation." (PMID 33799876, 2021). "Collectively, our results indicate that Sim1-Cre;Ntrk2lox/lox mice develop obesity due to increased food intake and reduced energy expenditure." (PMID 32265438, 2020). "The haploinsufficiency of SIM1 and MC4R due to loss-of-function mutations would lead to hyperphagic obesity." (PMID 32194858, 2020). "Sim1 haploinsufficiency in mice induces hyperphagia, obesity and central nervous system developmental abnormalities." (PMID 30926952, 2020). "Haploinsufficiency of Sim1, where one of the two gene copies is functionally lost, develops early-onset obesity with increased linear growth, hyperphagia, hyperinsulinemia and hyperleptinemia but no change in energy expenditure." (PMID 31124015, 2019). "We identified six different novel variants within five obesity-related genes (SIM1, POMC, PCSK1, MC4R and LEPR) in seven out of 105 children with early-onset severe obesity in a Turkish population." (PMID 30991789, 2019). "Six novel variants were identified in five candidate genes in seven out of 105 children with severe obesity; two in SIM1 (p.W306C and p.Q36X), one in POMC (p.Y160H), one in PCSK1 (p.W130G fs Ter8), two in MC4R (p.D126E) and one in LEPR (p.Q4H)." (PMID 30991789, 2019). "In both cases, hypothalamic Sim1 expression restored to normal levels and thus rescued the obesity syndrome." (PMID 31124015, 2019). "Our findings implicate many genes previously associated with obesity (e.g. PTBP2, TMEM18, MYT1L, POU3F2, SIM1, SH2B1), and also identified other potentially relevant candidates including TAS1R3, ALOX5AP, and GAS6." (PMID 29441128, 2018). "Deletion of MRAP2 in Sim-1 expressing neurons leads to obesity in mice to a similar extent as in global Mrap2−/− animals pointing to these neurons, located also in the PVN, as key targets of MRAP2 action in metabolism regulation." (PMID 30352741, 2018). "Mice models showed that SIM1 haploinsufficient mice develop obesity and have higher stature likely due to early life hyperphagia, while SIM1 overexpression decreases food intake in mice." (PMID 28472148, 2017). "In conclusion, we identify MYT1Lmutations as a cause of syndromic obesity, and establish MYT1L as a member of the leptin-melanocortin-SIM1 pathway, with downstream loss of OXT associated with MYT1L mutations a potential therapeutic target." (PMID 28859103, 2017). "SIM1 deletion heterozygous mice have hypocellularity of the paraventricular nucleus and hyperphagic obesity." (PMID 28859103, 2017). "SIM1 acts downstream of the melanocortin 4 receptor (MC4R), and mutations in this gene are a major cause of monogenic obesity in humans." (PMID 28472148, 2017). "The current dominant screening for obesity identified single nucleotide substitutions in the Sim1 and Mc4r genes of obese pedigrees." (PMID 27585985, 2016). "The crucial role of PVN neurons in body weight regulation has been further verified by the development of obesity after the ablation of SIM1-positive PVN neurons in adult mice." (PMID 27585985, 2016).
Obesity (continued). "Sim1 heterozygous mice display hyperphagic obesity and reduced oxytocin expression in the hypothalamus." (PMID 27857842, 2016). "Homozygous Sim1 mice die perinatally, but heterozygous mutants exhibit hyperphagic obesity, increased body fat percentage, as well as higher levels of POMC expression and resistance to α-MSH." (PMID 25825681, 2015). "Losing one functional copy of Sim1 in mice leads to early-onset obesity, hyperinsulinemia, and hyperleptinemia." (PMID 25806089, 2015). "Severe early-onset obesity was observed in a girl with haploinsufficiency of SIM1, possibly acting upstream or downstream of MC4R (Holder, Butte & Zinn, 2000)." (PMID 25825681, 2015). "Selective knockout of Mrap2 in neurons expressing Sim1 also exhibit obesity, similar to global knockout of Mrap2, consistent with the idea that Sim1 expressing neurons are key regulators of energy balance." (PMID 25825681, 2015). "Further support for the involvement of SIM1 in obesity came from studies in which patients displayed Prader-Willie like phenotypes due to heterozygous mutations in SIM1." (PMID 25825681, 2015). "Noteworthy, the hyperphagic obesity of single-minded 1 (Sim1) haploinsufficient mice has been explained by reduced OT expression, whose obese phenotype can be rescued with OT treatment." (PMID 26042088, 2015). "Postnatal PVN-specific ablation of Sim1 combined with chow diet leads to a hyperphagic obesity phenotype." (PMID 25954163, 2015). "Postnatal chemical ablation of Sim1 expressing neurons leads to hyperphagic obesity and reduced expression of OXT and TRH." (PMID 25954163, 2015). "We found that mice with PVN-Sim1 neuron ablation, similar to mice with global Sim1 neuron ablation, exhibit early onset obesity with hyperphagia as the primary defect." (PMID 24260538, 2013). "Mice with PVN Sim1 neuron ablation, similar to mice with global Sim1 neuron ablation, exhibit early onset obesity with hyperphagia as the primary defect." (PMID 24260538, 2013). "To investigate the mechanisms for the resistance of mice with PVN Sim1 neuron ablation to HF diet, we examined mRNA expression of obesity-related genes in these two brain regions." (PMID 24260538, 2013). "Specific ablation of Sim1 neurons in the PVN results in profound obesity, increased food intake and decreased energy expenditure." (PMID 24260538, 2013). "We have previously shown that mice with global Sim1 neuron ablation exhibit obesity with hyperphagia as the primary defect." (PMID 24260538, 2013). "To investigate the role of PVN Sim1 neurons in HF diet induced obesity, we examined daily food intake of PVN Sim1 neuron ablated mice before and after switching from normal chow diet to a HF diet." (PMID 24260538, 2013). "Here we report diphtheria toxin mediated neuron specific ablation of Sim1 neurons in adult mice induces rapid onset hyperphagia and obesity with reduced energy expenditure." (PMID 22558467, 2012). "It is notable that the degree of obesity observed in these mice was inversely correlated with hypothalamic Sim1 expression such that mice with lower hypothalamic Sim1 expression were more obese." (PMID 22558467, 2012). "Sim1+/− mice and conditional postnatal Sim1−/− mice have normal energy expenditure measured in the pre-obese state and are hyperphagic and develop late onset obesity after age 6 weeks." (PMID 22558467, 2012). "To examine the participation of Sim1 neurons in energy expenditure regulation, we performed metabolic studies after DT injection and Sim1 neuron ablation but prior to the onset of obesity (wk 6 of the protocol)." (PMID 22558467, 2012). "In post-injection mice, we observed a strong inverse correlation between the degree of obesity and hypothalamic Sim1 expression." (PMID 22558467, 2012). "Single-minded 1 (SIM1) gene (chr.6q16.3, position:100,836,750-100,911,551; hg19) mutations are one of the few known causes of nonsyndromic and PWS- like monogenic obesity in both humans and mice." (PMID 22043167, 2011).
Obesity (continued). "This distinguishes the Snord116del mouse model from the genetic mouse models of obesity, including ob/ob, db/db, Sim1 haploinsufficiency, Mc4r deletion and others that lack proper homeostasis control." (PMID 18320030, 2008). "sim1 heterozygous deficient mice have a similar phenotype to MC4R deficient and lethal yellow mice, with obesity resistant to the effects of melanocortins." (PMID 17764572, 2007). "Restoration of normal mc4r expression in the PVN and a subpopulation of amygdala neurones, using sim1-Cre transgenic mice, prevented 60% of the obesity." (PMID 17764572, 2007). "First, single-minded homolog 1 (Drosophila) (SIM1) was identified in a girl with early-onset obesity and a de novo chromosomal translocation." (PMID 17196040, 2006). "One human SIM1 early onset obesity variant, SIM1.R171H, is within the PAS-A -AT-Hook region predicted to contact DNA and has been shown to possess only 30% of wildtype (WT) SIM1 activity, a trait that is shared with its paralog SIM2." (PMID 41495897, 2026). "Indeed, we found several variants in clinical databases or from previous early onset obesity cohorts which are predicted to disrupt PAS-loop-mediated DNA binding in NPAS4, HIF2α, or SIM1." (PMID 41495897, 2026). "Hence, loss of function or haploinsufficiency of the SIM1 protein results in a reduction in the MC4R neuronal populations in the paraventricular nuclei, contributing to hyperphagia and obesity, similar to the MC4R deficiency." (PMID 41516406, 2026). "Additionally, in a study of 25 patients with obesity from Guadeloupe, five heterozygous variants were identified in the MC4R, NTRK2, SH2B1, and SIM1 genes, with a frequency of approximately 10%." (PMID 40149731, 2025). "Important genes associated with monogenic obesity consist of leptin (LEP), leptin receptor (LEPR), proopiomelanocortin (POMC), prohormone convertase 1 (PCSK1), MC4R, single-minded homolog 1 (SIM1), brain-derived neurotrophic factor (BDNF), and its receptor NTRK2 (commonly referred to as TrkB)." (PMID 40428329, 2025). "Furthermore, despite little evidence, an evaluation of pituitary function should be considered in patients with severe obesity and genetic abnormality, especially regarding the SIM1 gene." (PMID 40428410, 2025). "These cells prominently participate in the control of energy homeostasis, as indicated by the increased food intake, reduced locomotor activity and energy expenditure, and severe obesity observed in mice depleted of TrkB throughout the PVN (Sim1-Cre:Ntrk2lox/lox)." (PMID 38672441, 2024). "However, SIM1 heterozygous mice are viable and develop severe hyperphagic obesity, with hyperleptinemia and hyperinsulinemia." (PMID 39876968, 2024). "In contrast, obesity could be induced by ablating Rai1 from Sim1-lineage neurons and, to a lesser extent, SF1-lineage neurons." (PMID 37956053, 2023). "In contrast, Gq knockout in Sim1 cells also causes obesity owing to hyperphagia, but does not change energy expenditure." (PMID 35020776, 2022). "It has been reported that Gs knockout in Sim1 cells causes obesity due to reduced energy expenditure but does not change food intake." (PMID 35020776, 2022). "Thus, dysfunction of several Sim1 neuron subpopulations likely contributes to the hyperphagic obesity of Sim1-cre;mir-7fl/fl mice." (PMID 36175420, 2022). "The arcuate nucleus was found to be the region most enriched by the 9 known human monogenic obesity genes, with the highest expression of Pomc, Pcsk1, and Lepr genes, followed by the embryonic hypothalamus, with prevalent expression of Sim1, Pomc, and Tub genes." (PMID 34283813, 2021). "SIM1 is involved in the regulation of energy homeostasis, and KIF1BP and MCHR2 are involved in the regulation of food intake, which in turn affects obesity risk." (PMID 32355558, 2020).